ZEB1 (zinc finger E-box binding homeobox 1)
Diseases named in the same sentence as ZEB1 in open-access papers (continued):
Sharing a sentence is not in itself a finding about the gene and the disease.
tumor (continued). "Numerous tumor-profiling studies reported that the miR-200 family is playing a central role in epithelial-to-mesenchymal transition (EMT) and that it is linked to the regulation of ZEB1 and 2, which harbors nine conserved miR-200 sites in its 3′UTR." (PMID 36499397, 2022). "Hyaluronic acid (HA), a major extracellular matrix proteoglycan that is synthesized mainly by hyaluronic acid synthase 2 (HAS2), combines with CD44s to activate the expression of ZEB1 in tumor cells, indicating that HAS2 and ZEB1 form a positive feedforward loop." (PMID 35454770, 2022). "Nude mouse xenografts suggest that ZEB1 increases tumor growth and metastasis in vivo." (PMID 35404029, 2022). "Moreover, ZEB1/miR-200 plays an essential role in embryonic development and malignant tumour progression." (PMID 36499447, 2022). "Furthermore, IHC analysis of mouse tumor tissues revealed that Biochanin A suppressed ZEB1 and PD-L1 expression in vivo as well." (PMID 35242187, 2022). "Furthermore, ZEB1 expression occurs early in gastric carcinoma development to promote tumor progression and metastasis." (PMID 35454770, 2022). "ZEB1 knockdown has been implied to inhibit the invasive and metastatic ability of tumor cells." (PMID 36512117, 2022). "Moreover, ZEB1 suppresses the expression of stemness-inhibiting miR-200 and miR-203 and promotes tumor proliferation and progression." (PMID 36494341, 2022). "Additionally, PD-L1 is a downstream target of the miR-200/ZEB1 axis, known to facilitate immunosuppression in the tumor milieu." (PMID 36230658, 2022). "Besides, circ_0000808 silencing also had an inhibition on the expression of ZEB1 and vimentin in tumor tissues." (PMID 36192755, 2022). "For instance, the tumor‐promoting role of ZEB1 has been widely reported." (PMID 35601657, 2022). "Deletion of ZEB1 prevents tumor cells from invading and migrating." (PMID 36076302, 2022). "Similarly, circRNA_0084043 and circ-ZNF652 was suggested to derepress SNAIL expression through sponging of miRNAs and has-circ-000684, which is upregulated in gastric cancer cell lines and tumor tissues, derepresses ZEB1 by sponging miR-186." (PMID 36114510, 2022). "Activation of MEK1/2 and ERK1/2 promotes tumour progression by ZEB1 and ZEB2." (PMID 36499447, 2022). "ZEB1 is known as an epithelial marker to down-regulate the expression of e-cadherin to affect the epithelial-mesenchymal transition and thus participate in the invasion and metastasis of tumor cells." (PMID 35354376, 2022). "Interestingly, the tumour cells (identified by EpCAM expression) expressed very high levels of the mesenchymal CRC markers ZEB1 and HTR2B, which can be used to distinguish mesenchymal-like CRC (now commonly referred to as CMS4) from non-mesenchymal CRC." (PMID 35296803, 2022). "Moreover, the Wnt/β-catenin pathway promotes GBM aggregation and tumor malignancy via activation of EMT inducers such as ZEB1, Twist, and Snail." (PMID 36402997, 2022). "However, critical reappraisal of these data points to functional differences between EMT-TFs in tumor progression, underscoring the relevance of Zeb1 for plasticity and metastasis of pancreatic cancer." (PMID 36497278, 2022). "In addition, the tumor tissues of oe-circ_0000658-treated mice exhibited reduced β-catenin and E-cadherin, as well as elevated N-cadherin, Slug, Snail, ZEB1 and Twist, whereas further inhibition of HMGA2 reversed this effect relative to oe-circ_0000658 alone." (PMID 35031054, 2022). "Culture medium from ZEB1-overexpressing tumor cells induces proliferation of myofibroblasts." (PMID 35159011, 2022). "We confirmed that circRAPGEF5 could upregulate ZEB1 expression, and ZEB1 knockdown could reverse the tumor-promoting effect of circRAPGEF5, indicating that ZEB1 is a major target of circRAPGEF5 to exert its function in LAD." (PMID 35342341, 2022). "Therefore, our data uncover an alternative mechanism of Zeb1-mediated aerobic glycolysis as a driver of breast tumorigenesis by stimulating tumor–macrophage interplay." (PMID 35246504, 2022).
tumor (continued). "miR-200c targets ZEB1 to control the proliferation and invasion of tumor stem cells." (PMID 35805066, 2022). "The ZEB1 promoter remains, simultaneously, in an active and inactive epigenetic state, tipping the balance towards one or the other depending on the stimuli in the tumour microenvironment." (PMID 35267409, 2022). "ZEB1, a transcription factor associated with EMT-mediated tumor metastasis, has been shown to promote ferroptosis by directly inhibiting GPX4 activity, as well as in part through ZEB1-induced upregulation of PPARγ, a master regulator of hepatic lipid metabolism." (PMID 35847022, 2022). "In addition, Zeb1 plays an important role in tumor progression and poor clinical outcome in cancer patients." (PMID 34074001, 2021). "Additionally, interstitial-space–related genes, such as matrix metalloproteinase 1 (MMP1), MMP9, cathepsin, and zinc finger-binding homeobox 1 (ZEB1), play an important part in tumor metastasis." (PMID 33842351, 2021). "Previous studies have described the role of miR-200 family members, including miR-200a, miR-200b, miR-200c, and miR-429-3p in the regulation of expression of the E-cadherin transcriptional repressors ZEB1, ZEB2, and CRKL previously implicated in EMT and tumor metastasis." (PMID 33692799, 2021). "Moreover, EMT can induce reduction in KRAS dependency of tumor cells (KRAS addiction) and different ZEB1 thresholds drive KRAS‐dependent tumor initiation and metastasis capacities." (PMID 34459003, 2021). "In addition, as the downstream proteins of the PI3K/AKT signaling pathway, c‐Myc and ZEB1 play an important role in regulating the activity (proliferation, invasion, and migration) of tumor cells." (PMID 34531986, 2021). "Previous study showed proinvasive tumor cells fully expressed ZEB1 to obtain stem-like phenotype." (PMID 34969774, 2021). "Photographs of tumours and tumour weights showed that ZEB1 silencing inhibited tumour cell growth." (PMID 33960640, 2021). "In basal-like tumor subtypes with BRCA-mutations, ZEB1 expression may occur late in the oncogenic process depending on high POLQ expression in order to survive with the HR deficiency." (PMID 34458275, 2021). "miR-205 is known to suppress EMT of tumor cells by targeting ZEB1 and SIP168." (PMID 34475402, 2021). "In tumor research, ZEB1 is closely related to the occurrence and development of various tumors." (PMID 33391437, 2021). "Berberine suppressed EMT in tumor cells through overexpression of E-cadherin and suppression of N-cadherin, fibronectin, vimentin, Snail, Slug, and zinc finger E-box binding homeobox 1 (Zeb1) expression." (PMID 34220337, 2021). "Moreover, ZEB1 is inappropriately highly expressed in various malignant tumors and functions as a stimulating factor of tumor invasion and bone metastasis." (PMID 34109218, 2021). "Moreover, EXO facilitated the EMT in the tumor xenograft model mice after irradiation, manifesting as the upregulations of ZEB1, N-cadherin, β-catenin, and vimentin, and the downregulation of E-cadherin." (PMID 34462422, 2021). "Our results suggest that PRRX1 controls metabolism, has a tumour suppressive role, and may function in cooperation with ZEB1/2." (PMID 34496784, 2021). "Similarly, ATM-mediated stabilization of ZEB1 plays an important role for the enhanced accurate DNA repair ability by HR pathway of radioresistant tumor cells." (PMID 34458275, 2021). "Moreover, in comparison with normal control, the expression of ZEB1 was notably upregulated in tumor samples compared with normal control." (PMID 34796112, 2021). "Our results showed that no clinical factors, such as tumor size or prognosis, were significantly associated with the upregulation of ZEB1 expression." (PMID 34234851, 2021). "Additionally, the ZEB2:ZEB1 expression alterations in the transient early-activated antiviral CD8 effector cells are similar to the EMT response in some tumours." (PMID 34070208, 2021). "ZEB1 plays a crucial role in EMT during tumor carcinogenesis." (PMID 33670230, 2021).
tumor (continued). "Finally PDPK1 and ZEB1/2 members drive tumor metastasis spread via regulating epithelial–mesenchymal transition (EMT) during hypoxia." (PMID 34924998, 2021). "In addition, PCAT6 also upregulates the ZEB1 level by absorbing miR-143-3p in Osa, promoting cell proliferation, migration, invasion, and cell cycle in vitro, and tumor growth in vivo." (PMID 34885209, 2021). "Similarly, ZEB1 can promote tumor cell dissemination and metastasis, repressing the expression of the miR-200 members." (PMID 34439740, 2021). "In this study, we showed that the DCAF15-CUL4 E3 ligase complex functions as a tumor suppressor that promotes ZEB1 ubiquitination and degradation, which suppresses malignant phenotypes such as cell proliferation, migration and invasion as well as EMT in HCC cells." (PMID 33833131, 2021). "In addition, the mRNA level of genes ZEB1, Cyclin D1 and Survivin related to tumor prognosis were also significantly down-regulated." (PMID 34095137, 2021). "While knockdown of CDK6, ZEB1, and Sec23a expression compromised mammosphere formation, tumor cell migration, and/or clustering of MDA-MB-231 cells, only siCDK6 partially mimicked siICAM1 in inhibiting lung colonization of MDA-MB-231 cancer cells within 7 days after tail vein injection." (PMID 34381029, 2021). "The UTRs of Snail and Zeb1 are targeted by tumor suppressive miR-34a and miR-200, respectively." (PMID 34502497, 2021). "ZEB1 overexpression is known to facilitate tumor progression, invasion, and metastasis." (PMID 34070805, 2021). "Recently, the miR-200–Zeb1 axis has been genetically dissected in vivo, where knockouts of pro-epithelial miR-200 family members or mutations in miR-200 ZFGX1a binding sites lead to increased levels of Zeb1, induce EMT and promote tumor progression." (PMID 34072345, 2021). "In vitro studies have shown that the miR-200 family(miR-200a, miR-200b, and miR-200c) is downregulated in TNBC cells and demonstrated a tumor-suppressive action mediated mainly through downregulation of EMT by targeting ZEB1/2, SIP1 and BMI1 proteins, inhibiting PKC and mediating TGFβsignaling." (PMID 33572395, 2021). "Tumor growth of GRPs was significantly suppressed by knockdown of ZEB1 expression." (PMID 33764690, 2021). "Recently, the EMT regulatory miR-200/ZEB1 axis was shown to attune PD-L1 expression in tumor cells." (PMID 34065396, 2021). "Considering the important role of ZEB1 in tumor metastasis, we thus focused on another two genes." (PMID 34490263, 2021). "Current research suggests that EMT transcription factors like SNAI1, TWIST1 and ZEB1 may contribute to the promotion of tumor metastasis and drug resistance by EMT." (PMID 35127731, 2021). "Furthermore, FBXO45 modulated the process of EMT via mediating the ubiquitination and degradation of substantial EMT-related transcription factors, such as Twist1, Snai1/2, and Zeb1/2, in tumor cells." (PMID 35046938, 2021). "Moreover, miR-145 and miR-205-5p respectively target OCT4 and ZEB-1 and ZEB-2, associated with EMT and tumor invasion capacity." (PMID 34830097, 2021). "Previous studies have also revealed that ZEB1 expression is increased in tumor tissues." (PMID 34796112, 2021). "Another study showed that a loss of function in PARP-1 activated the epithelial–mesenchymal transition pathway through the increased expression of N-cadherin and ZEB-1 and the decreased expression of E-cadherin and β-catenin, which promote tumour progression through the TGF-β signalling pathway." (PMID 34830749, 2021). "ZEB1 and ZEB2 are EMT-associated transcription factors involved in tumor metastasis." (PMID 34226299, 2021). "In addition, many microRNAs can regulate the expression of E-cadherin and induce the production of EMT in tumor cells by regulating the transcription repressors ZEB1 and SIP1." (PMID 33992097, 2021). "Furthermore, IHC analysis showed high expression of GOLPH3, CD133, and ZEB1 in the tumor tissues formed by A549-GOLPH3 cells." (PMID 34671013, 2021).
tumor (continued). "As the UTR transcript of EMT genes and tumor suppressive miRs were tightly co-regulated, we hypothesized that the UTRs of Snail and Zeb1 compete with tumor suppressive miRs and are reciprocally regulated by a trans-regulatory network." (PMID 34502497, 2021). "Finally, in vivo experiment showed that knockdown of ZNRD1‐AS1 alleviated tumor growth by upregulating miR‐194 and downregulating ZEB1 in xenograft model." (PMID 32862492, 2020). "In conclusion, in this pilot study, we have shown that measurement of EMT markers (E-cadherin, vimentin, claudin-1, and ZEB1) as well tumor-suppressive miR-205 allows for robust retrospective discrimination of localized ESD-resected and regional surgically resected samples." (PMID 32093260, 2020). "Then ZNRD1‐AS1, miR‐194 and ZEB1 abundances were examined in tumor tissues." (PMID 32862492, 2020). "Despite these developments, much remains unknown about the role of ZEB1 in metastasis, a complex and multistep process where cancer cells hijack the normal developmental networks for tumor progression and metastasis." (PMID 32014049, 2020). "Taken together, we might speculate that HEK-EBNA293-VEGF-D cells underwent EMT-like processes driven by increased number of cells expressing TWIST-1 and ZEB-1 at the tumor periphery, thus acquiring an invasive phenotype." (PMID 33085676, 2020). "A novel, more specific inhibitors and a better understanding of ZEB1-driven plasticity, inflammation, and vascularization within the tumor and/or pre-metastatic niche microenvironments are inevitably needed to more effectively control resistance to various types of therapies." (PMID 32266287, 2020). "Overall, miR-128 could serve as an important regulator of tumor immunity through the ZEB1/CD47 axis and EMT in PDAC." (PMID 32536914, 2020). "Tumor cells that are undergoing EMT are characterized by loss of epithelial markers such as E-cadherin and/or gain/increased expression of mesenchymal markers such as ZEB1." (PMID 32641854, 2020). "Consequently, ZEB1 has been considered as a major actor of cancer cell plasticity in tumor initiation, progression, and metastatic dissemination." (PMID 32545795, 2020). "Overall, ZEB1 is an important mediator to enhance the invasion and proliferation of tumor cells." (PMID 32664703, 2020). "Therefore, further investigations to reveal the contribution of various tumor microenvironmental factors to tumor progression will lead to a comprehensive understanding of ZEB1 in cancer." (PMID 32014049, 2020). "Zeb1 has previously been found to be present in C918 cell lines, driving cellular proliferation through the repression of cyclin-dependent kinase inhibitors and tumor suppressor genes, as well as promoting tissue invasion and metastases." (PMID 31968535, 2020). "The tumor suppressor miR200c inhibits the epithelial–mesenchymal transition, a process involved in metastasis by enhancing the motility and migration of tumor cells, by targeting ZEB1 and ZEB2." (PMID 32498278, 2020). "MiRNAs, as post‐transcriptional regulator, have been recently found to play an important role in tumour progression, and we hypothesized that post‐transcriptional regulation by miRNAs may represent an upstream regulatory mechanism of ZEB1 expression." (PMID 32227618, 2020). "This suggests an important role for TAZ and ZEB1 in tumor invasion capacities and progression." (PMID 32545795, 2020). "Likewise, preventing mesenchymal transition by silencing ZEB1 or by pharmacological inhibition of the MMP9/PAR1 axis significantly reduced the ability of tumor cells to survive the anti-tumor activities of macrophages." (PMID 32809114, 2020). "Taken together, these data indicate that the expression of AGR2 may be attenuated in tumor cells directly by binding ZEB1 to the AGR2 promoter or indirectly by inhibition of miR-200c transcription." (PMID 32570918, 2020). "Besides, inhibition of ZNRD1‐AS1 attenuated the tumor growth by regulating miR‐194 and ZEB1 in vivo." (PMID 32862492, 2020).